SLC25A46 (solute carrier family 25 member 46)
Description:
Transmembrane protein of the mitochondrial outer membrane that controls mitochondrial organization. May regulate the assembly of the MICOS (mitochondrial contact site and cristae organizing system) complex which is essential to the biogenesis and dynamics of mitochondrial cristae, the inwards folds of the inner mitochondrial membrane. Through its interaction with the EMC (endoplasmic reticulum membrane protein complex), could regulate mitochondrial lipid homeostasis and thereby mitochondrial fission.
Synonyms: HMSN6B; PCH1E
Tractability: Antibody: UniProt predicts a signal peptide or a membrane-spanning region. PROTAC: ubiquitination databases record sites on it; its protein half-life has been measured.
Gene: Protein-coding gene on chromosome 5 (110,738,136 to 110,765,161, forward strand). Ensembl gene ENSG00000164209.
Subcellular location: Mitochondrion outer membrane
Subcellular location (Human Protein Atlas): Mitochondria
Gene Ontology:
Molecular function: protein binding; protein-containing complex binding
Biological process: cristae formation; mitochondrial fission; phospholipid homeostasis; protein-containing complex assembly; respiratory chain complex IV assembly; axon development; mitochondrial membrane fission; mitochondrion organization
Cellular component: mitochondrial outer membrane; mitochondrion
Genetic constraint (gnomAD): Loss-of-function variants: 16 observed, 17.67 expected, observed/expected ratio (o/e) 0.91, 90% interval 0.61 to 1.38. The upper end of that interval is the gene's LOEUF score, 1.38, which puts it in group 5 of 6, group 1 being the genes least tolerant of losing a copy. Missense variants: 414 observed, 374.35 expected, observed/expected ratio (o/e) 1.11, 90% interval 1.02 to 1.2. Synonymous variants: 168 observed, 134.73 expected, observed/expected ratio (o/e) 1.25, 90% interval 1.1 to 1.42.
Gene-disease validity (ClinGen):
ClinGen rates the evidence that SLC25A46 causes each of these diseases.
neuropathy, hereditary motor and sensory, type 6B (autosomal recessive): Definitive. Any hereditary motor and sensory neuropathy type 6 in which the cause of the disease is a mutation in the SLC25A46 gene.
Leigh syndrome (autosomal recessive): Limited. A progressive neurological disease defined by specific neuropathological features associating brainstem and basal ganglia lesions.
Homologues: Orthologues: chimpanzee SLC25A46 (100% identical), macaque SLC25A46 (99% identical), rabbit SLC25A46 (94% identical), pig SLC25A46 (94% identical), mouse Slc25a46 (89% identical), rat Slc25a46 (89% identical), guinea pig SLC25A46 (84% identical), dog SLC25A46 (79% identical), tropical clawed frog slc25a46 (72% identical), zebrafish slc25a46 (71% identical), Drosophila melanogaster Slc25A46a (33% identical), Drosophila melanogaster Slc25A46b (32% identical), and 1 more.
Diseases named in the same sentence as SLC25A46 in open-access papers:
SLC25A46 is named in the same sentence as 40 diseases in open-access papers, as found by Europe PMC text mining. Sharing a sentence is not in itself a finding about the gene and the disease. The quoted sentences say what the papers report.
optic atrophy (21 papers, 2016 to 2025). A disorder characterized by loss of optic nerve fibers. "A mitochondrial protein SLC25A46, originally identified as a cause of optic atrophy and spastic paraplegia, shares weak similarities with Ugo1." (PMID 40444356, 2025). "Human SLC25A46 has been identified as a causative gene for neurodegenerative disorders, such as Charcot–Marie–Tooth disease and optic atrophy." (PMID 40444356, 2025). "The four affected individuals in three families showed the homozygous mutation in the SLC25A46 with a consistent phenotype of childhood onset, optic atrophy, speech problems, and gait." (PMID 39202429, 2024). "The first mutations in SLC25A46 were reported in four patients with biallelic loss-of-function mutations who presented with cerebellar atrophy, optic atrophy, and Charcot–Marie–Tooth type 2." (PMID 36977595, 2023). "Optic Atrophy 3 (OPA3) and Solute Carrier Family 25 Member 46 (SLC25A46) are associated with recessive inherited complex neurodegenerative disorders that include optic atrophy as a key feature (Costeff syndrome and CMT with cerebellar atrophy, respectively)." (PMID 33806088, 2021). "In contrast, the recessive variants identified in SPG7 (8.47%), OPA1 (5.08%), and SLC25A46 (1.69%) were associated with syndromic optic atrophies." (PMID 33841295, 2021). "SLC25A46 mutations have been found to lead to mitochondrial hyper-fusion and reduced mitochondrial respiratory function, which results in optic atrophy, cerebellar atrophy, and other clinical symptoms of mitochondrial disease." (PMID 33985528, 2021). "Variants in SLC25A46 produce a wide spectrum of clinical features, with optic atrophy and axonal neuropathy shared by most all patients." (PMID 33426505, 2020). "Variants in SLC25A46 express range of disease, although all patients express optic atrophy and axonal neuropathy." (PMID 33426505, 2020). "A recent study reported mutations in SLC25A46 in patients with optic atrophy, axonal Charcot–Marie–Tooth disease (CMT), and cerebellar atrophy, and in a patient with an optic atrophy spectrum disorder, but neither study elucidated its molecular function." (PMID 27390132, 2016). "Prompted by this phenotypic association, other inherited forms of optic atrophy associated with CMT disease have been recently described with recessive mutations in SLC25A46 and C12orf65." (PMID 27696015, 2016). "SLC25A46 gene mutations have been identified in patients with Leigh syndrome, autosomal recessive cerebellar ataxia, progressive myoclonic ataxia with optic atrophy, Charcot-Marie Tooth syndrome 2, and lethal pontocerebellar hypoplasia." (PMID 35668433, 2022). "Mutations in the SLC25A46 (solute carrier family 25 member 46) gene, which plays a role in mitochondrial dynamics, have been also related to pontocerebellar hypoplasia and progressive myoclonic ataxia with optic atrophy and neuropathy." (PMID 33917666, 2021). "SLC25A46 (solute carrier family 25 member 46) mutations have been linked to various neurological diseases with recessive inheritance, including Leigh syndrome, optic atrophy, and lethal congenital pontocerebellar hypoplasia." (PMID 34945750, 2021). "In our study we created a knockout model of slc25a46 gene, which is a recently discovered important player in mitochondrial dynamics, and deleterious mutations in which are known to cause peripheral neuropathy, optic atrophy and cerebellar ataxia." (PMID 32208444, 2020). "SLC25A46, a novel mitochondrial protein, has recently been identified as a pathogenic target in a wide spectrum of rare genetic neurological diseases, including optic atrophy, Charcot-Marie-Tooth type 2, Leigh syndrome, progressive myoclonic ataxia and lethal congenital pontocerebellar hypoplasia." (PMID 28376086, 2017). "Variants in SLC25A46 are associated with PCH1E, and other manifestations include HMSN, optic atrophy, ataxia and Leigh syndrome." (PMID 40428407, 2025).
optic atrophy (continued). "In yeast overexpression systems, SLC25A46 interacts with mitofusin 2 (MFN2) and optic atrophy 1 (Opa1) genes which are associated with CMT2A (MFN2) and optic atrophy (Opa1)." (PMID 40428407, 2025). "SLC25A46 mutations are also associated with a variety of diseases in addition to the lethal PCH1, such as Leigh syndrome and optic atrophy." (PMID 38347586, 2024). "Mice with Slc25a46 dysfunction developed severe motor impairment, optic atrophy, and developmental defects of the nervous system, as well as premature death." (PMID 33985528, 2021). "Similar to previous SLC25A46 case reports, the proband described here presented with a phenotype consistent with a mitochondrial disorder, including optic atrophy, brain MRI findings, elevated lactate levels, and early death." (PMID 34945750, 2021). "Two mouse Slc25a46 mutant models have shown to develop cerebellar ataxia, optic atrophy, peripheral neuropathy, and neuromuscular junction defects." (PMID 32208444, 2020). "Before genetic testing results, involvement of mitochondrial genes such as the SLC25A46 gene or the OPA3 gene has been evoked because of their known association with severe form of sensory motor axonal neuropathy, optic atrophy and gastrointestinal dysmobility." (PMID 38348452, 2024). "As the converging phenotype of SLC25A46-mediated pathologies is optic atrophy, we further investigated whether atc/atc mice develop histological optic lesions." (PMID 28376086, 2017). "Additionally, the phenotypic spectrum of SLC25A46 expanded, including the severe infantile Leigh-like encephalopathy, but also severe congenital ponto-cerebellar hypoplasia and more recently optic atrophy and Parkinsonism, this latter case resembling some specific OPA1 mutations." (PMID 33806088, 2021). "Loss of function of SLC25A46 is associated with lethal PCH, contrasting other variants causing non-lethal optic atrophy." (PMID 40428407, 2025). "Although the substrates of Slc25a46 have not been identified, dysfunction of this gene results in neuropathy including Charcot-Marie-Tooth type 2, Leigh syndrome, and optic atrophy." (PMID 32502168, 2020). "Furthermore, alteration of SLC25A46’s functions might also result in species-specific phenotype, as all human cases reported so far suffer from optic atrophy, which is not observed in the bovine and mouse models reported here." (PMID 28376083, 2017).
Leigh syndrome (11 papers, 2016 to 2025). "In conclusion, we have identified two novel variants, one in the splice donor region of intron 1 (c.283+5G>A) and the other a missense variant (c.1039C>T, p.Arg347Cys) in the SLC25A46 gene in a proband with Leigh syndrome-like presentation." (PMID 34945750, 2021). "Here, we show that a member of the mitochondrial metabolite carrier family, SLC25A46, that we found mutated in Leigh syndrome, an early‐onset neurodegenerative disease, is the likely orthologue of Ugo1." (PMID 27390132, 2016). "This study identifies SLC25A46 as a key player in human mitochondrial architecture, and, when mutated, as a cause of classical Leigh syndrome, an early‐onset neurodegenerative disease." (PMID 27390132, 2016). "We uncovered a homozygous missense mutation in SLC25A46, the mammalian orthologue of Ugo1, in a subject with Leigh syndrome." (PMID 27390132, 2016). "The mitochondrial protein SLC25A46 has been recently identified as a novel pathogenic cause in a wide spectrum of neurological diseases, including inherited optic atrophy, Charcot-Marie-Tooth type 2, Leigh syndrome, progressive myoclonic ataxia and lethal congenital pontocerebellar hypoplasia." (PMID 28376086, 2017). "The newly identified links between MFN2, OPA1, MICOS, and EMC indicate that SLC25A46 mechanistically couples lipid flux between the ER and mitochondria directly at outer/inner mitochondrial membrane contacts, contributing to our understanding of the molecular pathology underlying Leigh syndrome." (PMID 27390132, 2016).
neuropathy (5 papers, 2017 to 2024). A disorder affecting the nervous system that manifests with pain, tingling, numbness, and/or muscle weakness. "Mice with knockout of slc25a46 (solute carrier family 25 member 46), a nuclear gene encoding mitochondrial transmembrane protein, display premature aging phenotypes characterized by shortened life span, defective motor ability and redox imbalance in the brain, and neuropathy." (PMID 37055865, 2023).
axonal neuropathy (4 papers, 2017 to 2022). Any nerve disorder affecting the axon of a nerve. "Recessively inherited mutations in SLC25A46 (solute carrier family 25 member 46), which may inhibit mitochondrial fission, can cause childhood-onset optic atrophy, axonal neuropathy, and cerebellar neurodegeneration." (PMID 35879298, 2022).
Cerebellar atrophy (4 papers, 2016 to 2024). Cerebellar atrophy is defined as a cerebellum with initially normal structures, in a posterior fossa with normal size, which displays enlarged fissures (interfolial spaces) in comparison to the foliae secondary to loss of tissue. "Hence mutations in the SLC25A46 gene could cause a lethal form of PCH with cerebellar atrophy." (PMID 38347586, 2024).
cerebellar ataxia (3 papers, 2020 to 2025). A neurological syndrome characterized by clumsy and uncoordinated movement of the limbs, trunk, and cranial muscles. "The pathogenic mechanism investigation using SLC25A46 knockout mice discovered that animals lacking SLC25A46 have severe ataxia, which is mostly caused by Purkinje cell degeneration." (PMID 36157077, 2022).
and sensory neuropathy (2 papers, 2018 to 2024). "Diseases associated with the Slc25a46 gene include hereditary motor and sensory neuropathy." (PMID 30537945, 2018).
polyneuropathy (2 papers, 2019 to 2022). A disease or disorder affecting more than one nerve. "The cases illustrate the disease spectrum and provide substantial information to the knowledge of polyneuropathy caused by SLC25A46 variants." (PMID 36578309, 2022).
pontocerebellar hypoplasia (2 papers, 2019 to 2021). Pontocerebellar hypoplasias (PCH) are a rare heterogeneous group of diseases characterized by hypoplasia and atrophy and/or early neurodegeneration of the cerebellum and pons. "Interestingly, different mutations in SLC25A46, that cause loss of function of the mutant protein, were also found in patients with the pontocerebellar hypoplasia (PCH)." (PMID 31096646, 2019).
atopic dermatitis (1 paper, 2019). "Previously, genome studies had linked SLC25A46 to atopic dermatitis but a high expression of the SLC25A46 transcript had been observed in the spinal cord, cerebellum, and optic chiasm neurons of patients." (PMID 31096646, 2019).
Hearing impairment (1 paper, 2025). A decreased magnitude of the sensory perception of sound. "Hearing impairment, which affected nearly 15% of the reported families, was mainly observed in Wolfram syndrome and autosomal dominant hearing impairment caused by WFS1 variants, followed by variants of POLG, OPA1, DNMT1 and SLC25A46." (PMID 39423307, 2025).
hereditary motor and sensory neuropathy (1 paper, 2018). A group of slowly progressive inherited disorders affecting motor and sensory peripheral nerves. "SLC25A46 and MFN2 are associated with Hereditary Motor and Sensory Neuropathy (HMSN) while HUWE1 is associated with X-linked syndromic mental retardation, Turner type (XMRT)." (PMID 29342083, 2018).
left ventricular hypertrophy (1 paper, 2013). Enlargement of the LEFT VENTRICLE of the heart. "Rs17132261, within SLC25A46, encodes a mitochondrial phosphate transporter, implying abnormal myocardial energetics contribute to left ventricular hypertrophy development." (PMID 23879873, 2013).
neuroblastoma (1 paper, 2017). Neuroblastoma (NB) is the most common solid, extracranial childhood tumor. "The mitochondrial localization of mouse SLC25A46 was confirmed by immunoblot analysis in WT central nervous system (CNS) tissues and by fluorescence microscopy upon expression of a chimeric SLC25A46-EGFP protein in the N2A mouse neuroblastoma cell line." (PMID 28376086, 2017).
mitochondrial disease (3 papers, 2021 to 2023). "In addition to the two widely-studied mitochondrial proteins OPA1 and MFN2, mutations in SLC25A46 have also been identified as a pathogenic cause in a spectrum of neurological and mitochondrial diseases." (PMID 34945750, 2021).
neurological diseases (3 papers, 2017 to 2025). "This is consistent with the genotype of human individuals with pathogenic SLC25A46 variants; most pathogenic SLC25A46 variants cause neurological disorders in an autosomal recessive manner." (PMID 40444356, 2025). "Functional point mutations in the SLC25A46 gene have recently been reported in heterogeneous neurological disorders." (PMID 28376086, 2017).
peripheral neuropathy (3 papers, 2020 to 2025). A disorder affecting the peripheral nervous system. "Intriguingly, pathogenic variants in many of the peripheral neuropathy proteins discussed here lead to hyperfused mitochondrial networks (e.g., SLC25A46, DRP1, MFF, GDAP1, MYH14)." (PMID 33810506, 2021). "The peripheral neuropathy phenotype, which is present in most patients with pathogenic SLC25A46 variants, is thought to be due to a combination of increased fusion leading to hyperfused mitochondrial networks and altered mitochondrial distribution." (PMID 33810506, 2021). "Notably, SLC25A46 knockout mice have peripheral neuropathy with axonal degeneration and demyelination." (PMID 33810506, 2021).
movement disorder (1 paper, 2021). Neurological conditions resulting in abnormal voluntary or involuntary movement, which may impact the speed, fluency, quality and ease of movement. "Using AAV-Slc25a46, Yang and colleagues ameliorated SLC25A46-related mitochondrial hyperfusion in a murine model and recovered the movement disorder and sciatic nerve demyelination, extending the longevity of the Slc25a46−/− mouse." (PMID 34708072, 2021).
SLC25A46 also shares sentences with these, for which no sentence is quoted: Charcot-Marie-Tooth type 2 (4 papers); mitochondrial neurogastrointestinal encephalomyopathy (3); asthma (2); neurodegenerative disease (2); Parkinson disease (2); Ataxia (1); autosomal recessive cerebellar ataxia (1); Barth syndrome (1); Charcot-Marie-Tooth disease (1); Costeff syndrome (1); eczema (1); familial focal epilepsy (1); Friedreich ataxia (1); hay fever (1); liver disease (1); liver fibrosis (1); motor neuron degeneration (1); neurodevelopmental disorder (1); neuromuscular disease (1); pontocerebellar hypoplasia, type 1E (1); tumor (1); Wolfram syndrome (1).